MYC (MYC proto-oncogene, bHLH transcription factor)
Diseases named in the same sentence as MYC in open-access papers (continued):
Sharing a sentence is not in itself a finding about the gene and the disease.
Sepsis (12 papers, 2018 to 2025). Sepsis is defined as life-threatening organ dysfunction caused by a dysregulated host response to infection. "Finally, transcription factor MYC may be an important regulatory gene in the underlying dysfunction of sepsis-induced acute respiratory distress syndrome (ARDS)." (PMID 36830965, 2023). "The result of CCK-8 assay showed that silencing MYC inhibited cellular proliferation of sepsis in absenceor presence of LPS treatment." (PMID 32779435, 2020). "This study aimed to explore the potential mechanism of MYC proto-oncogene, BHLH Transcription Factor(MYC) gene, on sepsis." (PMID 32779435, 2020). "Studies have shown that MYC may be involved in the process of LPS-induced sepsis by promoting cell proliferation and inhibiting apoptosis, and MYC may reduce inflammation during the progression of LPS-induced sepsis." (PMID 35957694, 2022). "MYC might take part in the process of LPS induced sepsis through suppressing apoptosis and inducingcell proliferation." (PMID 32779435, 2020). "Moreover,Flow cytometry assay showed that MYC silencing contributed to the apoptosis of sepsis cells." (PMID 32779435, 2020). "MYC might take part in the process of LPS induced sepsis via promotingcell proliferation and inhibiting cell apoptosis." (PMID 32779435, 2020). "The effect of MYC gene silencing on sepsis cells had been investigatedby qRT-PCR and Western blot." (PMID 32779435, 2020). "This study explored thepotential mechanism of MYC in sepsis." (PMID 32779435, 2020). "From the perspective of the centrality of the PPI network, this result suggests that most of the interacting and bottleneck genes like NFKB1, SRC and MYC could have important roles in the pathogenesis of sepsis." (PMID 30297806, 2018). "Genes such as MYC (a transcription factor, TF), SELL, and LGALS3 (associated with cold shock domain-containing protein A) may act as upstream regulators or potential therapeutic targets in the context of glycosylation dysfunction related to sepsis." (PMID 40672940, 2025). "Regarding the gene sets found in the functional analysis of the present review, studies have documented that the transcription factor MYC may be an important regulatory gene in the dysfunction of sepsis or acute respiratory distress syndrome (ARDS) secondary to sepsis." (PMID 37893128, 2023). "Moreover, MYC mightreduce inflammation during the progression of LPS induced sepsis." (PMID 32779435, 2020). "Thus, we speculated that MYC might reduceinflammation during the progression of LPS induced sepsis." (PMID 32779435, 2020). "Thus,we speculated that MYC might contribute to the cell proliferation inLPS-induced sepsis." (PMID 32779435, 2020). "However, flow cytometry assay inthis study showed that silencing MYC promoted apoptosis in sepsis cells.This result indicated that MYC might suppress but not induce apoptosiswithin progression of disease." (PMID 32779435, 2020).
bladder tumor (11 papers, 2014 to 2025). "To investigate the effect of MYC K412 methylation on bladder tumor growth, we mutated the endogenous MYC K412 into arginine in HT1197 cells using CRISPR‐cas9 gene editing." (PMID 40091385, 2025). "We looked for other ways to disrupt the FGFR3/MYC loop in bladder tumors bearing FGFR3 mutations." (PMID 29463565, 2018). "Among them, 13 genes, including AHR, BCL2L1, CCND1, KRAS, SOX4, MYC, and E2F family genes, were previously reported to have increased expression in BC tissue, and their alterations, either through amplification or upregulation, are linked with bladder tumor initiation or progression." (PMID 40801146, 2025). "In summary, this study reveals that the SETD8/MYC axis is a novel regulatory mechanism essential for bladder tumor growth both in vitro and in vivo." (PMID 40091385, 2025). "We found that MYC, as one of the core drivers of bladder tumor growth and progression, is a novel substrate of SETD8 and can be methylated at K412." (PMID 40091385, 2025). "Knocking down SETD8 or using the SETD8 specific inhibitor UNC0379 substantially reduces the protein level of MYC and inhibits the bladder tumor growth in vitro and in vivo." (PMID 40091385, 2025). "Since these results supported such involvement of MYC and E2F activators, we decided to measure their expression in a more extensive dataset including 77 bladder tumours and their corresponding normal samples." (PMID 31316092, 2019). "Using RT112 and MGH‐U3 xenograft models treated for 9 days with a pan‐FGFR inhibitor, PD173074, which delayed tumor growth, we also showed in vivo that FGFR3 and MYC were involved in a positive feedback circuit inducing bladder tumor growth." (PMID 29463565, 2018). "Based on the results presented here, we devised a model for this newly identified FGFR3/MYC positive feedback loop involved in bladder tumor cell proliferation (Graphical abstract)." (PMID 29463565, 2018). "We demonstrated that JQ1 prevented BRD4 binding to the MYC promoter and enhancer, thereby inhibiting MYC expression and, consequently, the growth of bladder tumor cells expressing activated forms of FGFR3 both in vitro and in vivo in xenograft." (PMID 29463565, 2018). "Consistently, we found that human bladder tumors bearing FGFR3 mutations had levels of FGFR3 and MYC expression that were positively correlated." (PMID 29463565, 2018). "In light of its key role downstream from FGFR, MYC inhibition appears to be a valuable therapeutic strategy for bladder tumors with FGFR3 alterations." (PMID 29463565, 2018). "SUMOylated SETD8 enhances MYC K412 methylation, further promoting bladder tumor growth." (PMID 40091385, 2025). "A relevance of this loop to human bladder tumors was supported by the positive correlation between FGFR3 and MYC levels in tumors bearing FGFR3 mutations, and the decrease in FGFR3 and MYC levels following anti‐FGFR treatment in a PDX model bearing an FGFR3 mutation." (PMID 29463565, 2018). "Interestingly, studies of MYC mRNA levels and of the phosphorylation of p38 and AKT in human bladder tumor samples harboring FGFR3 mutations suggested that this loop might also operate in tumors." (PMID 29463565, 2018). "Moreover, MYC expression was positively correlated with FGFR3 expression in bladder tumors harboring a mutated FGFR3, whereas no such correlation was observed in tumors bearing wild‐type FGFR3 (n = 122)." (PMID 29463565, 2018). "This could be related to a specific FGFR3‐induced MYC transcriptomic program in bladder tumors." (PMID 29463565, 2018). "By catalyzing the methylation of MYC at lysine 412 (K412), SETD8 strongly stabilizes MYC and promotes bladder tumor growth." (PMID 40091385, 2025). "Further, we discovered that MYC is a novel substrate of SETD8, underscoring the critical role of SETD8 in bladder tumor progression." (PMID 40091385, 2025).
bladder tumor (continued). "Pharmacological inhibition of SETD8 with UNC0379 ameliorates bladder tumor growth, highlighting the potential of targeting the SETD8/MYC axis as a therapeutic strategy for BC." (PMID 40091385, 2025). "To this end, we performed GSEAs using gene sets related to transcriptional profiles of these TFs and found that NFKB-related gene signatures (NFKB-GS), but not those of MYC, are enriched in aggressive bladder tumors." (PMID 40026699, 2025). "MYC rearrangement was found in the bladder tumor but not in the nasal tumor." (PMID 33335784, 2020).
breast adenocarcinoma (11 papers, 2004 to 2023). "Notably, elegant studies illustrated that breast adenocarcinomas induced by conditional MYC overexpression but that also subsequently develop mutations in K-Ras fail to undergo sustained regression upon MYC inactivation." (PMID 18461184, 2008). "As a MYC antagonist, MNT was originally considered a tumour suppressor and this was supported by an early study showing that mice with mammary-specific Mnt deletion developed mammary adenocarcinoma." (PMID 36755068, 2023). "For example, the mammary adenocarcinoma in a mouse model established by MYC overexpression could not regress after abolishing MYC expression because of a secondary spontaneous activating mutation in Kras." (PMID 25612309, 2015).
cutaneous melanoma (11 papers, 2015 to 2025). A primary melanoma arising from atypical melanocytes in the skin. "MYC amplification, seen in our case, is common in solid tumors including breast and liver adenocarcinoma; however, it is also prevalent in cutaneous melanoma." (PMID 39329865, 2024). "NBN followed MYC had the highest amplification rate in mucosal group (8/25, 32.0%) and acral group (5/15, 33.3%), compared to that in cutaneous melanoma (4/41, 9.8%, p = 0.045 and p = 0.048)." (PMID 35688842, 2022). "In vitro experiments have confirmed that high expression of c-MYC is positively correlated with the aggressiveness of cutaneous melanoma, and the inhibitor can effectively inhibit tumor growth." (PMID 35688842, 2022). "It has been reported that PHF10 is over-expressed in cutaneous melanoma and interacts with MYC, to recruit the PBAF complex to pro-proliferative loci, and promote cell cycle progression." (PMID 35323214, 2022). "Increased copy number gains in 8q24 at MYC have been detected in 90% of cutaneous melanomas in humans." (PMID 34422947, 2021). "MYC amplification was verified to most commonly occur in mucosal and acral melanoma, with frequencies of 44.0% (11/25) and 40.0% (6/15) respectively, which were significantly higher than that in cutaneous melanoma (3/41, 7.3%, p = 0.001 and p = 0.008)." (PMID 35688842, 2022). "On the other hand, combining discriminant isoforms from different clinical classes in the same tumor type, only five of the 12 tumor types tested show enriched hallmarks, which include the enrichment of MYC targets in skin cutaneous melanoma (SKCM) and kidney papillary carcinoma (KIRP)." (PMID 27535130, 2016). "We also included a cutaneous melanoma cell line, C8161, which has extra copies of MYC, and no Gnaq/11 mutations." (PMID 26397223, 2015).
Immunodeficiency (11 papers, 2018 to 2025). Failure of the immune system to protect the body adequately from infection, due to the absence or insufficiency of some component process or substance. "Chr8q contains numerous cancer-critical genes, including MYC (8q24), which is well-studied across various cancers, including MPNST, where upregulation of MYC and or its targets was correlated with tumor recurrence and immune deficiency." (PMID 39857943, 2025). "It has been shown that MYC expression is also associated with many immune diseases, such as myasthenia gravis, sicca syndrome, psoriasis, etc." (PMID 39660984, 2024). "MYC is a positive effector of tissue inflammation and can cause immune diseases." (PMID 33193630, 2020). "More specifically, we found replication for the majority of the top pathways: E2F targets, mTOR and MYC pathways identified in a large mega-analysis based on gene expression in blood, and immunodeficiency in a meta-analysis using multiple tissues." (PMID 31719968, 2019). "The c-MYC protein represents an early molecular marker of cell cycle activity, which may be important in the development of immune diseases." (PMID 33193630, 2020).
leiomyosarcoma (11 papers, 2012 to 2025). An uncommon, aggressive malignant smooth muscle neoplasm, usually occurring in post-menopausal women. "Indeed, MYC overexpression in a subset of leiomyosarcomas was associated with decreased metastasis-free survival." (PMID 26555296, 2015). "LPD showed CDK4, NBN, DAXX, MYC moderately, and strongly positive, and uterine leiomyosarcoma displayed strongly positive." (PMID 32359372, 2020). "Activated MTOR/AKT1 signaling, RASSF1 hypermethylation and MYC expression can also be found in a subset of leiomyosarcomas." (PMID 29881541, 2018). "Compared to wild-type mouse embryonic fibroblasts (MEFs) and NIH-3T3L1 cells, MYC protein levels were higher in the leiomyosarcoma cell lines." (PMID 26555296, 2015). "For leiomyosarcoma, MYC amplification was shown to have an adverse prognostic impact." (PMID 29765529, 2018). "MYC protein levels were elevated in both murine leiomyosarcoma cell lines." (PMID 26555296, 2015). "The immunohistochemistry staining analysis of CDK4, MYC, NBN, and DAXX in uterine leiomyoma (10 cases), LPD (4 cases), and leiomyosarcoma (10 cases) was subsequently conducted." (PMID 32359372, 2020). "In our current analysis we found that this difference regarding MYC was not significant in comparison to leiomyosarcomas." (PMID 29881541, 2018).
liposarcoma (11 papers, 2007 to 2025). A usually painless malignant tumor that arises from adipose tissue.
liver disease (11 papers, 2012 to 2025). "Intriguingly, we found that also low carbohydrate-high fat ketogenic diet, which we previously showed to have an unexpected beneficial effect on the liver disease in the Bcs1lp.S78G mice, dampened the MYC induction, limited the DNA damage, and moderated excessive hepatocyte proliferation." (PMID 37731815, 2023). "The MYC expression levels were differential among the different clinical stages of liver diseases." (PMID 36120320, 2022). "Moreover, new data suggest that c-MYC deregulation in liver disease is more common than expected, and not only restricted to HCC development, but it also includes many other chronic liver diseases, such as alcoholic liver disease (ALD)." (PMID 28422055, 2017). "Therefore, the main purpose of this review is to: (i) link c-MYC with different types of liver pathology; (ii) describe the possible mechanisms of action; and finally, to (iii) discuss ongoing efforts in targeting the unique properties of c-MYC for the treatment of liver disease." (PMID 28422055, 2017). "Furthermore, mIHC analysis revealed a significantly elevated presence of hepatic MYC+ ECs and MMP12+ Mψ in cases of human DILI (including AILI and non‐AILI groups) compared to other liver diseases, highlighting the disease‐specific nature of the microenvironment." (PMID 38350725, 2024). "The purpose of this review is to broaden the understanding of the general functions of c-MYC, to focus on c-MYC-driven pathogenesis in the liver, explain its mode of action under basal conditions and during disease, and discuss efforts to target c-MYC as a plausible therapy for liver disease." (PMID 28422055, 2017).
metastatic prostate carcinoma (11 papers, 2014 to 2026). A carcinoma that arises from the prostate gland and has spread to other anatomic sites. "Data sets with significant down regulation of PrKD1 in metastatic prostate cancer were identified, and the gene expression data for MYC, MAX and MXD1 were compared." (PMID 29108267, 2017). "COMMD3: BMI1 fusion expression and COMMD3 protein increases significantly in metastatic prostate cancer; COMMD3 activates oncogenes such as c-MYC, promotes prostate proliferation, migration and invasion; Increased COMMD3 expression is positively correlated with tumor recurrence and reduced survival." (PMID 36776284, 2023). "Although up-regulation of MYC in most neoplastic tissues is a very early event that contributes to self-renewal and proliferation, localized prostate cancer (PCa) is not proportionally as hyperproliferative as metastatic prostate cancers which frequently harbor focal amplification of MYC." (PMID 32681068, 2020).
myocardial infarction (11 papers, 2015 to 2026). Gross necrosis of the myocardium, as a result of interruption of the blood supply to the area, as in coronary thrombosis. "Endothelial-specific overexpression of MYC was sufficient to induce type H bone endothelial cells, whereas inhibition of NLRP3-dependent IL-1β production partially prevented the post-myocardial infarction loss of type H vasculature in mice." (PMID 34172720, 2021). "Myocardial infarction associated transcript could regulate the expression of ENC1, and MYC could bind to the promoter region of ENC1." (PMID 33551826, 2020). "In line with this, transient expression of both MYC and Cyclin T1 by a single intramyocardial dose of a modified RNA coding for both genes was shown to be a potential regenerative therapeutic in the heart after myocardial infarction, inducing cell cycle and division of cardiomyocytes." (PMID 38510176, 2024). "However, MYC activation could be an option to favour regeneration in the heart after myocardial infarction or hypoxia." (PMID 38510176, 2024).
T-cell leukemia (11 papers, 2013 to 2024). A malignant disease of the T-lymphocytes in the bone marrow, thymus, and/or blood. "MYC binds to HIF2α gene promoter preferentially in Sca1+ cancer stem cells (CSCs) in a MYC-driven mouse T-cell leukemia model and the equivalent ABCG2+ CSC population in human acute lymphoblastic lymphomas and activates HIF2α expression." (PMID 33251216, 2020). "FACS analysis of four PIM1/MYC mice and one mouse from PIM2, PIM3, and BCLxl cohorts demonstrates only myeloid cell (GR-1 and CD11b) markers, indicating a myeloid, not T-cell leukemia." (PMID 25238262, 2014).
atherosclerosis (10 papers, 2017 to 2025). A disease characterized by the build-up of fatty material and calcium deposition in the arterial wall resulting in partial or complete occlusion of the arterial lumen. "MYC is an exciting target because it has been associated with atherosclerosis by promoting smooth muscle cell proliferation, and we showed that it is also upregulated in ECs from human coronary atherosclerotic plaques." (PMID 35079076, 2022). "Previous studies have shown that increased expression of c-MYC protein is closely associated with certain cardiovascular diseases, such as atherosclerosis, hypertension and restenosis." (PMID 34326694, 2021). "The elevated expression of ACTB and MYC was also detected in epicardial adipose tissue samples from patients with CAD, implying their paracrine modulatory role in the development of atherosclerosis." (PMID 39080630, 2024). "fold: 6.81) in MYC HME cells were involved in lipid metabolism, including atherosclerosis signalling, LXR/RXR activation, and PPAR signalling (black boxes)." (PMID 31942031, 2020).
rectal adenocarcinoma (10 papers, 2020 to 2025). "Consistent with this, a computational study of the MYC expression network from the Cancer Genome Atlas (TCGA) showed that high MYC expression in colon and rectum adenocarcinoma positively correlates with pathways associated with translation, ribosomes, and rRNA." (PMID 32455578, 2020). "In a further analysis, we determined the alteration frequencies of c-Met/GSK3β/MYC/CCND1 gene signatures in CRC, COAD, and rectal adenocarcinoma (READ) tissues." (PMID 36672275, 2023).
thyroid tumor (10 papers, 2016 to 2025). A benign or malignant neoplasm affecting the thyroid gland. "These mutations synergistically drive the occurrence of thyroid tumours through the ATF4 and c‐MYC pathways." (PMID 32926483, 2020). "However, the present studies uncovered a novel epigenetic action of trametinib to suppress MYC transcription, leading to inhibition of thyroid tumor growth." (PMID 30459933, 2018). "Studies in thyroid tumors suggest that Metformin increases p AMPK, reduces mTOR phosphorylation, downregulates S6K1/S6 signaling, and inhibits cyclin D1 and c MYC via the mTOR pathway." (PMID 41156128, 2025).